MCM3AP-AS1 (MCM3AP antisense RNA 1)
Synonyms: FLJ10508; NCRNA00031; C21orf85; MCM3AP-AS; MCM3APAS; MCM3APASB
Gene: Long non-coding RNA gene on chromosome 21 (46,228,394 to 46,284,359, forward strand). Ensembl gene ENSG00000215424.
Diseases named in the same sentence as MCM3AP-AS1 in open-access papers:
MCM3AP-AS1 is named in the same sentence as 5 diseases in open-access papers, as found by Europe PMC text mining. Sharing a sentence is not in itself a finding about the gene and the disease. The quoted sentences say what the papers report.
liver cancer (1 paper, 2019). An epithelial or non-epithelial malignant neoplasm that arises from the liver. "The role of long non-coding RNA (lncRNA) Minichromosome Maintenance Complex Component 3 Associated Protein (MCM3AP) Antisense RNA 1 (MCM3AP-AS1) has been analyzed in liver cancer." (PMID 31836002, 2019).
tumor (3 papers, 2019 to 2023). "MCM3AP antisense RNA 1 (MCM3AP-AS1) is a newly identified potential tumor biomarker." (PMID 35783010, 2022). "A novel lncRNA MCM3AP-AS1 (also known as MCM3APAS), which was 2.84-fold higher in HCC tissues than that in adjacent non-tumor tissues, caught our attention." (PMID 30782188, 2019). "lncRNA MCM3AP antisense RNA 1 (MCM3AP-AS1) was also overexpressed in HCC tissues and cell lines and positively correlated with large tumor size, high tumor grade, advanced tumor stage, and poor prognosis, indicating that the knockdown of MCM3AP-AS1 inhibits HCC growth." (PMID 36769116, 2023).
MCM3AP-AS1 also shares sentences with these, for which no sentence is quoted: glioblastoma (1 paper); hepatocellular carcinoma (1); non-small cell lung carcinoma (1).